CRP (C-reactive protein)
Diseases named in the same sentence as CRP in open-access papers (continued):
Sharing a sentence is not in itself a finding about the gene and the disease.
metastasis (9 papers, 2014 to 2025). The spread or migration of cancer cells from one part of the body (where they first appeared) to another. "Multivariate analysis indicated that histological variants, liver metastasis, low serum Alb levels (Alb < 3.3 g/dL), and high serum CRP levels (CRP > 1.9 mg/dL) were significant independent poor prognostic factors." (PMID 38592548, 2024). "Multivariate logistic regression analysis showed ALP, CRP, Hb and ESR associated with SRE and skeletal metastasis." (PMID 37489216, 2023). "A correlation between an increase in serum CRP level or a decrease in serum albumin levels with the presence of peritoneal metastasis has been discovered." (PMID 32968368, 2020). "Both the CRP SNP rs7553007 and KRAS/BRAF mutations were independent prognostic factors for CRC patients with synchronous liver metastasis." (PMID 23755178, 2014). "However, the incidence of lung/liver metastasis at baseline was neither associated with baseline IL-6 or CRP levels nor with the best response to chemotherapy." (PMID 35965580, 2022). "The results showed that the presence of the A-allele at CRP SNP rs7553007 (HR = 1.101; 95% CI = 1.011–1.200; P = 0.027) and KRAS/BRAF mutations (HR = 2.377; 95% CI = 1.293–4.368; P = 0.005) were independent prognostic factors in CRC patients with synchronous liver metastasis." (PMID 23755178, 2014). "Furthermore, the CRP SNP rs7553007 (hazard ratio [HR] = 1.101; 95% confidence interval [CI] = 1.011–1.200; P = 0.027) and KRAS/BRAF mutations (HR = 2.377; 95% CI = 1.293–4.368; P = 0.005) remained predictive for the CSS of CRC patients with synchronous liver metastasis in multivariate analysis." (PMID 23755178, 2014). "However, median survival time (MST, P = 0.006), age (P = 0.009), extra pleural metastasis (P = 0.040), WBC (P = 0.013), albumin (P = 0.006), CRP (P < 0.001), CYFRA (P = 0.431), ESR (P < 0.001), NLR (P < 0.001), PLR (P < 0.001), and LMR (P = 0.049) had significant differences among the three groups." (PMID 31837116, 2020).
morbid obesity (9 papers, 2017 to 2024). An excess of body weight, normally defined as an individual with a body mass index greater than 35 or a body weight greater than one hundred percent of ideal body weight. "Subclinical inflammation in AT is systemic in morbid obesity, which can be confirmed by positive associations of the plasma level of chemerin with CRP in patients with T2DM (r = 0.76, p < 0.01)." (PMID 30871547, 2019). "Consequently, using CRP to estimate overall disease risk or prognosis may be misleading in subjects with morbid obesity." (PMID 32646381, 2020). "Patients with morbid obesity showed typical signs of chronic inflammation characterized by increased levels of CRP and fibrinogen." (PMID 37266430, 2023). "Elevations in CRP concentrations are usually much lower in conditions with chronic low-grade inflammation like morbid obesity or atherosclerosis." (PMID 31776403, 2019).
myasthenia gravis (9 papers, 2017 to 2025). Myasthenia gravis (MG) is a rare, clinically heterogeneous, autoimmune disorder of the neuromuscular junction characterized by fatigable weakness of voluntary muscles. "Diagnostic workup for suspected immune-related myositis and myasthenia gravis should include blood testing for creatine kinase, aldolase, erythrocyte sedimentation rate, C-reactive protein and antibody testing (AChR, striational and muscle-specific tyrosine kinase)." (PMID 39897316, 2025). "The immunomodulatory feature of MEPED was demonstrated by a significant decrease in C-reactive protein (CRP) in serum during objective response, as well as a robust neurological improvement in a patient with severe myasthenia gravis who did not qualify for dose-intensive therapy." (PMID 40183103, 2025).
myopia (9 papers, 2017 to 2025). "Previous studies have indicated that anaphylactic disease (allergic conjunctivitis, allergic rhinitis) and proinflammatory factors (C-reactive protein) increase myopia’s risk and severity of myopia." (PMID 36229775, 2022). "Despite the scant research on the CRP-myopia nexus and its ambiguous mechanism in myopia’s progression, our consensus across IVW, weighted median, and MR-Egger analyses reaffirms the negative correlation between CRP levels and myopia exposure." (PMID 39239046, 2024). "By leveraging an expansive dataset, our exploratory study endeavours to shed light on the intricate relationship between CRP and myopia development." (PMID 39239046, 2024). "Our research delineates a reverse relationship regarding genetically proximate circulating CRP concentrations and myopia." (PMID 39239046, 2024). "In Random Forest algorithm, we also identified the moderate importance of C-reactive protein in predicting high myopia." (PMID 36229775, 2022). "Conversely, lower levels of C-reactive protein (CRP) (IVW estimate OR: 0.996, 95% CI: 0.994–0.999, P=0.002) and tumour necrosis factor alpha (IVW estimate OR: 0.995, 95% CI: 0.994–0.996, P<0.001) were robustly linked to a heightened risk of myopia." (PMID 39239046, 2024). "Noteworthy findings include significant associations of IL-2 [IVW odds ratio (OR): 1.003, 95% CI: 1.001–1.005, P=0.001], IL-2ra (IVW OR: 1.002, 95% CI: 1.000–1.003, P=0.049), CRP (IVW OR: 0.996, 95% CI: 0.994–0.999, P=0.002), and TNF-α (IVW OR: 0.995, 95% CI: 0.994–0.996, P<0.001) with myopia risk." (PMID 39239046, 2024). "Furthermore, a separate investigation employing a machine learning paradigm to identify risk factors for severe myopia found that CRP did not exacerbate the risk or severity of the condition." (PMID 39239046, 2024). "Some studies have linked serum inflammatory biomarkers like C-reactive protein (CRP) and white blood cell (WBC) count to a higher prevalence of myopia." (PMID 39703523, 2024). "A diverse range of complement-related genes were differentially-expressed, with components and regulators of both the classical and alternate pathways up-regulated in late myopia (CS1, PROS1, C1QB and CFD) and late hyperopia (SERPING1, C1QA, CRP, C7 and CFD)." (PMID 28852117, 2017). "Our finding intimates that CRP and TNF-α might serve as protective elements against myopia’s evolution." (PMID 39239046, 2024). "Together with the results of our study, it is reasonable to assume that local proinflammation factors, rather than systematic factors (such as C-reactive protein), promote myopia onset and progression." (PMID 36229775, 2022). "Furthermore, the detection of CRP index in blood, BCVA, and myopia control helped detect EOC, which is also an important topic worthy of follow-up discussion." (PMID 35566498, 2022).
oral disease (9 papers, 2020 to 2026). "Herein, our results show that 28 NCDs, including five types of cancer, and circulating levels of CRP were strongly associated with oral diseases." (PMID 36494387, 2022). "Systemic inflammation, as observed by an increase in the serum levels of C-reactive protein, and other biomarkers resulting from PD may be considered as one pathway by which this oral disease increases the risk of various LCs." (PMID 33138320, 2020). "Investigating how factors such as oral hygiene, inflammation, or oral diseases can affect salivary CRP concentrations will elucidate the relationship between salivary and serum CRP levels." (PMID 38741881, 2024).
rheumatic fever (9 papers, 2013 to 2024). A post-bacterial multisystem inflammatory disease occurring as a post-infectious, nonsuppurative sequela of untreated streptococcus pyogenes (Group A streptococcus [GAS]) pharyngitis, and mainly occurs in individuals aged 5 to 15 years. "The first clinical use for determination of CRP in the blood, developed at the Rockefeller Institute by H. C. Anderson and Maclyn McCarty, employed antibodies to CRP in a capillary precipitin test as a marker of disease activity in acute rheumatic fever." (PMID 36936978, 2023). "C-reactive protein is increased in patients with acute rheumatic fever." (PMID 33638745, 2021). "ARF: acute rheumatic fever; CRP: C-reactive protein; ESR: erythrocyte sedimentation rate; and GAS: group A streptococcal infection." (PMID 39618634, 2024). "However, the efficacy of long-acting penicillin for secondary prevention of rheumatic fever has not been widely studied; consequently, the relation between serum levels of long-acting penicillin and inflammatory markers C-reactive protein and interleukin-6 is largely unknown." (PMID 33638745, 2021).
streptococcal infection (9 papers, 2017 to 2025). Any of the several infectious disorders caused by members of streptococcus, a genus of gram positive bacteria belonging to the family Streptococcaceae. "The most common test performed on these patients was the COVID-19 antigen test, used in 26.6% of cases, while chest X-rays, C-reactive protein rapid tests, and rapid antigen detection tests for streptococcal infection were seldom used." (PMID 41560722, 2025). "Markers of recent streptococcal infection or persistent inflammation including elevated ASO titer (p = 0.01) or elevated CRP (p = 0.001) during follow-up were also predictive of mortality." (PMID 28061759, 2017). "Conversely, eliminating streptococcal infection may reduce the relapse/recurrence of IgAV by decreasing CRP and IL-8 levels." (PMID 37753071, 2023). "Notwithstanding this, it might be appropriate to consider ARF with minor Jones criteria (arthralgia, low-grade fever of unknown origin, and elevated ESR/CRP/acute phase reactants), especially when there is a connection to possible contact with streptococcal infection." (PMID 40724633, 2025). "For instance, streptococcal infection, the most common infectious trigger for childhood IgAV, may induce or enhance the production of CRP and IL-8 by activating the immune system and endothelial cells, thereby leading to complement system activation and inflammation." (PMID 37753071, 2023). "Since streptococcal infection is a major pathogenesis of RHD, we evaluated the serum level of RF, ASO and CRP between the two groups." (PMID 28662157, 2017).
testicular cancer (9 papers, 2015 to 2025). A primary or metastatic malignant neoplasm that affects the testis. "Based on correlation analyses, we found that the thiols group level was significantly associated with AGR (directly) and CRP (inversely), reflecting the complex interdependence of oxidative stress and inflammation in testicular cancer." (PMID 35629255, 2022). "Despite few data demonstrating that CRP is associated with staging or survival in testicular cancer it was shown to be a biomarker of post-treatment complications in testicular cancer survivors." (PMID 35756636, 2022). "A Norwegian cohort study of 586 men with testicular cancer also observed an association between serum levels of C-reactive protein (CRP) and development of second primary tumours and cardiovascular disease." (PMID 28900475, 2017). "We aimed to compare the values of CBC-derived inflammatory markers and C-reactive protein (CRP) between patients with testicular cancer and a control group." (PMID 41283275, 2025). "This study aimed to evaluate the diagnostic and prognostic utility of CBC-derived inflammatory indices and CRP in patients with testicular cancer." (PMID 41283275, 2025). "This suggests that CRP may serve as a potential marker of cardiovascular events in long-survival testicular cancers." (PMID 35756636, 2022). "Protein levels of a candidate biomarker were measured in testicular cancer patient plasma before, during and after bleomycin-etoposide-cisplatin chemotherapy, and related to endothelial damage biomarkers (von Willebrand Factor (vWF), high-sensitivity C-Reactive Protein (hsCRP))." (PMID 25590623, 2015). "So, even though a high CRP level shows that there is a lot of inflammation in the body, a high NLR level gives a more detailed picture of the immune system, showing both the short-term reaction and the long-term suppression of the immune system in the case of testicular cancer." (PMID 41283275, 2025).
vitamin B12 deficiency (9 papers, 2009 to 2025). A disease characterized by low serum levels of vitamin B12, either inherited or acquired. "Accordingly, the risk of vitamin B12 deficiency was more than fivefold higher in our patients with increased CRP values, and the association remained after adjusting for metformin use." (PMID 33026590, 2021).
Acidosis (8 papers, 2016 to 2024). Abnormal acid accumulation or depletion of base. "Metabolic acidosis will aggravate this inflammatory reaction, leading to the increase of CRP level in patients." (PMID 39574951, 2024). "Laboratory investigations were significant for metabolic acidosis and an increased C-reactive protein (CRP) 14.5 mg/dL (0.0 - 0.6 mg/dL)." (PMID 38807822, 2024). "In the present ordinal logistic regression analysis, we found that GDM, initial FiO2 value, invasive ventilation, acidosis, hypochloremia, CRP level, PDA and positive respiratory culture were independent risk factors for BPD severity." (PMID 36357648, 2023). "In conclusion, in this single-center study, GDM, initial FiO2 value, invasive ventilation, acidosis, hypochloremia, CRP level, PDA and positive respiratory culture were independent risk factors for BPD severity and we developed machine learning models with good performance." (PMID 36357648, 2023).
alveolitis (8 papers, 2005 to 2025). "Less frequently required are specific immunoglobulin G (IgG) antibodies against antigens associated with hypersensitivity pneumonitis (72.6%), physical examination findings (61.1%), or C‐reactive protein (CRP) levels (42.5%)." (PMID 40913127, 2025). "Skin score (>14), skin involvement extent, autoantibodies pattern, FVC (≤ 79%), DLCO (≤ 49%), alveolar score on HRCT (> 6), IL-6 plasma levels (> 0.75 pg/ml) and CRP (> 5 mg/l) were the components of the logistic regression model for alveolitis." (PMID 16107215, 2005). "Erythrocyte sedimentation rate (ESR), C-reactive protein (CRP), and hypersensitivity pneumonitis panel were all within normal limits." (PMID 27965910, 2016). "Furthermore, consistent with previously reported data, serum HO-1 was positively correlated with serum LDH, CRP, and the GGO and consolidation score as markers of cellular damage and alveolitis in the lung." (PMID 36001619, 2022). "C reactive protein (CRP) values tended to be higher in patients with alveolitis (8.6 ± 10.8 mg/l) than in patients without alveolitis (6.6 ± 6.7 mg/l), but the difference between the two groups was not statistically significant." (PMID 16107215, 2005).
anaphylaxis (8 papers, 2014 to 2025). An acute hypersensitivity reaction that occurs from exposure to an allergen. "The patient’s clinical presentation included classic signs of anaphylaxis such as wheezing, a skin rash, and loss of consciousness, along with elevated CRP and transient ECG changes suggestive of cardiovascular stress." (PMID 39941456, 2025). "Other blood tests ordered in ED, such as EUC, CBE, LFTs and CRP, have limited clinical utility in anaphylaxis patients." (PMID 38627619, 2024). "Both CRP and histamine showed potential clinical utility for differentiation between anaphylaxis and other critical illness." (PMID 36003410, 2022). "Both CRP and histamine concentration showed good discrimination between anaphylaxis and other critical illness, with an AUROC of 0.96 (95% CI 0.91–1) and 0.81 (95% CI 0.69–0.93), respectively." (PMID 36003410, 2022). "C-reactive protein and histamine both had an AUROC >0.8; whereby dogs with anaphylaxis tended to have high histamine concentration and low CRP concentration, with the opposite occurring in dogs with critical illness." (PMID 36003410, 2022). "Subjects showed clinical signs of anaphylaxis with mild leukocytopenia and increased C-reactive protein concentrations, which are possibly related to the presence of relatively high circulating anti-CHIPS antibodies and suggest an inflammatory response." (PMID 32471891, 2020). "C-reactive protein likely takes at least 4 h to increase in circulation in dogs after an inflammatory stimulus, according to experimental models, whereas dogs with suspected anaphylaxis tend to present within 1–2 h of clinical signs." (PMID 36003410, 2022). "C-reactive protein, IL6, and KC concentrations were significantly higher in the critical illness group, compared to the anaphylaxis (CRP P < 0.0001, IL6 P < 0.001, KC P = 0.015) and healthy groups (CRP P < 0.0001, IL6 P < 0.0001, KC P < 0.0001)." (PMID 36003410, 2022). "This study also identified potential utility of serum CRP concentration, or a combination of serum histamine and CRP concentration, to distinguish anaphylaxis from non-anaphylactic illness." (PMID 36003410, 2022). "In contrast, the anaphylaxis group did not have significantly higher concentrations of these three biomarkers, compared to the healthy group (CRP P = 0.99, IL6 P = 0.17, KC P = 0.08)." (PMID 36003410, 2022). "In addition to CRP, plasma histamine concentration showed good discriminatory potential between dogs with anaphylaxis and non-anaphylactic critical illness, based on an AUROC of 0.81." (PMID 36003410, 2022).
cholelithiasis (8 papers, 2018 to 2026). The presence of crystallized deposits forming in the gallbladder or biliary tree, primarily composed of cholesterol, bilirubin, and bile. "The overall independent risk factors for cholelithiasis in patients who underwent PEG insertion were increased C-reactive protein (CRP) levels and decreased physical activity status (bedridden state)." (PMID 38086971, 2023). "In contrast, the genetic correlations between MetS and CRP, MetS and sleep apnoea, and MetS and cholelithiasis were driven solely by horizontal pleiotropy, indicating no causal relationship exists between these pairs." (PMID 40956352, 2025). "Multivariable MR analysis adjusted for alcohol consumption, BMI, cholelithiasis and C-reactive protein levels supported these findings." (PMID 39221257, 2024). "Abdominal imaging is recommended to confirm the presence of cholelithiasis and to consider prophylaxis for cholelithiasis, especially in bedridden patients with elevated initial CRP levels at the time of PEG insertion." (PMID 38086971, 2023). "Comparing both markers, the proteasome and C-reactive protein, we found that the type of surgery has an influence on the circulating 20S proteasome activity in contrast to C-reactive protein concentration which was not different in response to surgery due to an ovarian cyst or cholelithiasis." (PMID 30405319, 2018). "Proteasomes are more specific markers because there is a correlation between proteasome activity and the type of abdominal surgery in contrast to C-reactive protein concentrations which are not different in response to surgery performed in regard to ovarian cysts or cholelithiasis." (PMID 30405319, 2018).
chronic liver failure (8 papers, 2013 to 2025). Liver failure that develops slowly and gradually for some time, possibly for years, often as the result of cirrhosis, or malnutrition. "Patients with the high CRP profile showed higher MELD, CHILD, and Chronic Liver Failure Consortium (CLIF-C)-ACLF scores (P = 0.06, P = 0.03, and P = 0.002, respectively)." (PMID 30800122, 2019).